SNORD77B (small nucleolar RNA, C/D box 77B)
Gene: Small nucleolar RNA gene on chromosome 8 (100,004,583 to 100,004,649, forward strand). Ensembl gene ENSG00000212414.
Gene Ontology:
Biological process: RNA processing
Cellular component: nucleolus
Homologues: Orthologues: macaque SNORD77B (100% identical), zebrafish snord80.1 (60% identical), zebrafish snord80.2 (60% identical).